TUBA1C (tubulin alpha 1c)
Diseases named in the same sentence as TUBA1C in open-access papers (continued):
Sharing a sentence is not in itself a finding about the gene and the disease.
cancer (continued). "Herein, we examined the underlying relationship between the level of infiltration of 22 immune cell types and TUBA1C expression in different cancer types." (PMID 35513790, 2022). "Data retrieved from major public databases, such as TCGA, GEO, GTEx, GSCA, CancerSEA, HPA, and RNAactDrugs, revealed that TUBA1C expression was high in 33 cancer types." (PMID 36466547, 2022). "Specifically, the expression of TUBA1C mRNA in various cancer types was analysed and verified using data extracted from TCGA and GTEx databases." (PMID 36466547, 2022). "TIMER2.0 was used to visualise the relationship between TUBA1C expression and immune infiltration levels in different cancer types." (PMID 36466547, 2022). "The CancerSEA database was used to determine the functional state of TUBA1C in different cancer types at the single-cell level." (PMID 36466547, 2022). "In particular, the TAP1 gene was positively correlated with TUBA1C in almost all cancer types, indicating that TAP1 can serve as a promising immunotherapy target." (PMID 36466547, 2022). "Our research revealed that TUBA1C was significantly upregulated in 18 cancers, and immunohistochemistry confirmed consistent results for the protein expression levels of TUBA1C in cancers." (PMID 35513790, 2022). "TUBA1C is correlated with an unfavourable prognosis and the infiltration of immune cells in several cancers." (PMID 36466547, 2022). "In this study, the CancerSEA and GSCA databases were used to examine the mechanism of action of TUBA1C in pan-cancer." (PMID 36466547, 2022). "In this study, CYT scores and TUBA1C were positively correlated in most cancer types, especially in LGG, OV, GBM, and BLCA, which indicates that TUBA1C affects the prognosis of patients by affecting the activity of immune cells and the immune microenvironment." (PMID 36466547, 2022). "A significant correlation was observed between the CNVs and mRNA expression of TUBA1C in 18 cancer types." (PMID 36466547, 2022). "In this study, TUBA1C expression was found to be high in several cancer types, and survival analysis revealed that TUBA1C was a poor prognostic factor for >12 cancer types." (PMID 36466547, 2022). "We selected the TIICs with the highest correlation with TUBA1C expression in each cancer for demonstration." (PMID 35513790, 2022). "TUBA1C serves as a prognostic biomarker for a variety of cancers and ACER2 is a Golgi enzyme involved in regulating B1 integrin maturation and cell adhesion." (PMID 34685586, 2021). "Our findings suggest that TUBA1C serves as a potential prognostic marker and produces a novel molecular target in cancer therapy." (PMID 32117719, 2020). "Similarly, tubulin alpha chain 1C (TUBA1C), adhesion G‐protein coupled receptor G2 (ADGRG2), and nectin‐4 have been associated with cell migration and proliferation, albeit in cancer cell types." (PMID 39895030, 2025). "To expand the understanding of the role of TUBA1C across a wide range of cancers and tissues, we conducted a comprehensive analysis focusing on its association with CD274, variations in gene expression, CNV, and methylation discrepancies, in addition to their implications for prognosis." (PMID 39301023, 2024). "Additionally, TUBA1C has been shown to play an important role in cancer immunity, as its expression positively correlates with stromal and immune cells." (PMID 38891892, 2024). "Furthermore, our analysis of CNVuncovered significant deletions or amplifications of TUBA1C in many cancer types." (PMID 39301023, 2024). "Additionally, a CCK-8 assay demonstrated that both the viability and proliferative ability of these two cancer cell lines were markedly reduced following TUBA1C downregulation." (PMID 39301023, 2024). "Overall, TUBA1C appears to be involved in the development and progression of various types of cancer and may serve as a potential prognostic biomarker and therapeutic target." (PMID 38891892, 2024).
cancer (continued). "This relationship was also evident in a variety of normal tissues, such as the kidney, liver, skin, and brain, indicating that TUBA1C may play a pervasive role in contexts other than cancer." (PMID 39301023, 2024). "The overexpressed proteins, including actinin α1 isoform (ACTN1), annexin A5 (ANXA5), cathepsin D (CTSD), F-actin-capping protein subunit β (CAPZB), inorganic pyrophosphatase (PPA1), and tubulin α1c chain (TUBA1C), are related to cellular structure, growth, or cancer cell invasion." (PMID 38249992, 2024). "Although the exact mechanisms of TUBA1C in disease are still unclear, existing research suggests that TUBA1C may be a powerful potential prognostic marker of cancer progression and metastasis." (PMID 38032902, 2023). "Similarly, other additional tubulin isotypes TUBB2B, TUBB8, and TUBA1C, which I observed in first level of our selection steps, were previously reported to involve in nucleation of MT, cancer progression, oocyte maturation, and neuronal abnormalities." (PMID 37466845, 2023). "Therefore, the association between TUBA1C expression and the TME was investigated by assessing the relationships of stromal and immune scores to TUBA1C expression in 33 cancers using the ESTIMATE algorithm." (PMID 35513790, 2022). "We further explored the differential expression of TUBA1C in cancers in GEPIA." (PMID 35513790, 2022). "Furthermore, low expression of TUBA1C was found to be a protective factor for OS, PFI, and DFI in most cancer types but was found to be a risk factor for PRAD and COAD." (PMID 36466547, 2022). "The CNVs of TUBA1C in 33 cancer types were examined using GSCA." (PMID 36466547, 2022). "Our study indicated that TUBA1C might be a biomarker for predicting the immune status and prognosis of cancers, offering new ideas for cancer treatment." (PMID 35513790, 2022). "We used Oncomine to assess TUBA1C gene expression in 33 cancers." (PMID 35513790, 2022). "In this study, TUBA1C was strongly correlated with MDSCs in pan-cancer, indicating that MDSCs may be used to develop novel immunotherapy strategies in the future." (PMID 36466547, 2022). "TUBA1C was reported to be related to cell proliferation and the cell cycle in diverse cancers and was associated with the progression of several cancers, whereas no pancancer analysis has been performed for TUBA1C." (PMID 35513790, 2022). "In this study, TUBA1C and m6A-related genes were positively correlated in most cancer types." (PMID 36466547, 2022). "In these two cancer types, TUBA1C showed a positive correlation with all m6A-related genes." (PMID 36466547, 2022). "Further gene coexpression analysis was carried out between TUBA1C and immune-associated genes, including those encoding MHC molecules, chemokines, chemokine receptors, and proteins related to immune activation and immunosuppression, in 33 cancers." (PMID 35513790, 2022). "Furthermore, a positive correlation was observed between m6A-related genes and TUBA1C mRNA in most cancer types, especially in LIHC and TGCT." (PMID 36466547, 2022). "TUBA1C, a microtubule component, contributes to the development of several cancers." (PMID 34721547, 2021). "Our results demonstrated the TUBA1C played an important role in cancer immunity." (PMID 34721547, 2021). "TUBA1C is a microtubule component that is involved in a variety of cancers." (PMID 33653340, 2021). "In addition, pairwise difference analysis was performed on cancer and paracancerous tissues from the same sample taken from the TCGA database, and the results showed that TUBA1C expression in cancer tissues was significantly higher than that in paracancerous tissues (P = 1.446e-05)." (PMID 38032902, 2023). "Furthermore, the prognostic significance of TUBA1C CNVs in pan-cancer was examined." (PMID 36466547, 2022).
cancer (continued). "In this study, we first downloaded raw data on TUBA1C expression in cancers from The Cancer Genome Atlas (TCGA) database and multiple other databases and analysed these data with R software to investigate the prognostic and immunological value of TUBA1C in cancers." (PMID 35513790, 2022). "The TUBA1C and TUBB proteins are vital components of the microtubule network and are frequently dysregulated in cancer." (PMID 40867231, 2025). "TCGA data were used to examine the role of TUBA1C in predicting PFI, DFI, DSS, and OS in pan-cancer." (PMID 36466547, 2022). "Tubulin alpha-1c chain (TUBA1C), a subtype of α-tubulin, has been shown to be involved in cell proliferation and cell cycle progression in several cancers and to influence cancer development and prognosis." (PMID 35513790, 2022). "In particular, TUBA1C was positively correlated with all m6A-related genes in LIHC and TGCT, suggesting that TUBA1C affects cancer development by affecting m6A modification in LIHC and TGCT." (PMID 36466547, 2022). "TCGA data were used to examine the correlation between TUBA1C mRNA and MHC-related genes in pan-cancer." (PMID 36466547, 2022). "Therefore, TUBA1C may serve as a viable prognostic biomarker for immunotherapy of pan-cancer." (PMID 36466547, 2022). "It was shown that TUBA1C affected TMB in 16 cancers and affected MSI in 8 cancers, suggesting that the efficacy of ICI therapy can be predicted by TUBA1C expression." (PMID 35513790, 2022). "However, the function of TUBA1C in the onset and progression of pan-cancer remains unclear." (PMID 36466547, 2022). "The results demonstrated a positive correlation between TUBA1C and the infiltration of CD4+ T cells and MDSCs in most cancer types." (PMID 36466547, 2022). "Similarly, the expression of SLC3A2, TUBA1B, TUBA1C, TUBB, FSTL1, and INSIG1 was affected by FIRΔexon2, suggesting that FIR and FIRΔexon2 engage in the transcription of various cancer-related mRNAs." (PMID 38139171, 2023). "Moreover, the change in the expression of TUBA1C, PRDX4, LDHC, C7, and KNG1 due to NVA-AA treatment corroborated with the sensitivity provided by CTRP drugs to cancer cells." (PMID 37719007, 2023). "The results showed that TUBA1C had a positive correlation with most MHC-related genes in THCA, BLCA, and BRCA, and the TAP1 gene was positively correlated with TUBA1C in almost all cancer types, suggesting that TAP1 is a potential immunotherapeutic target." (PMID 36466547, 2022). "TUBA1C (r was range from 0.29 to 0.66), TUBA1B (0.21~0.65), P4HA1 (0.25~0.74), HSPA8 (0.17~0.60), CCNB1 (0.22~0.62) as the top five genes were highly correlated with glycolysis score across cancers." (PMID 32635458, 2020). "Since downregulation of TUBA1C and PRDX4 proteins was observed only in NVA-AA-treated MDA-MB-231 cells, their downregulated expressions might make MDA-MB-231 sensitive to NVA-AA treatment in the same fashion as shown by cancer cells to THZ-2-102-1 treatments." (PMID 37719007, 2023). "In addition, a negative relationship between TUBA1C expression and OS was observed in 8 cancers: BRCA (p = 0.011), KIRC (p = 0.016), LAML (p = 0.037), LGG (p < 0.001), LIHC (p < 0.001), LUAD (p = 0.003) and SKCM (p = 0.002)." (PMID 35513790, 2022). "Despite a lack of statistical significance in cancer grade, stage, and TNM classification between these groups, the group with high TUBA1C expression comprised a notably higher proportion of patients with advanced disease stages and grades." (PMID 39301023, 2024).
neurodegenerative disease (1 paper, 2023). A disorder of the central nervous system characterized by gradual and progressive loss of neural tissue and neurologic function. "Malfunction of microtubules (e.g., TUBA1C) is also considered as the central physiopathological mechanism of neurodegenerative diseases." (PMID 36970516, 2023). "TUBA1C is a member of Microtubules which are vulnerable to degradation and disorganization in a variety of neurodegenerative diseases." (PMID 36970516, 2023).
TUBA1C also shares sentences with these, for which no sentence is quoted: infection (4 papers); bladder urothelial carcinoma (2); clear cell renal cell carcinoma (2); colorectal cancer (2); pheochromocytoma (2); uterine carcinosarcoma (2); acute coronary syndrome (1); Alzheimer disease (1); astrocytoma (1); bile duct cancer (1); Cirrhosis (1); head and neck cancer (1); hematological malignancies (1); Huntington disease (1); immune dysfunction (1); legionellosis (1); lung squamous cell carcinoma (1); lymphoma (1); melanoma (1); myeloma (1); oesophageal cancer (1); osteosarcoma (1); ovarian serous cystadenocarcinoma (1); Pan (1); posterior uveitis (1); prostate carcinoma (1); rectal cancer (1); rectum adenocarcinoma (1); renal carcinoma (1); renal cell carcinoma (1).
A further 8 diseases each share a sentence with TUBA1C in 1 paper.